FLT3 (fms related receptor tyrosine kinase 3)
Description:
Tyrosine-protein kinase that acts as a cell-surface receptor for the cytokine FLT3LG and regulates differentiation, proliferation and survival of hematopoietic progenitor cells and of dendritic cells. Promotes phosphorylation of SHC1 and AKT1, and activation of the downstream effector MTOR. Promotes activation of RAS signaling and phosphorylation of downstream kinases, including MAPK1/ERK2 and/or MAPK3/ERK1. Promotes phosphorylation of FES, FER, PTPN6/SHP, PTPN11/SHP-2, PLCG1, and STAT5A and/or STAT5B. Activation of wild-type FLT3 causes only marginal activation of STAT5A or STAT5B. Mutations that cause constitutive kinase activity promote cell proliferation and resistance to apoptosis via the activation of multiple signaling pathways.
Synonyms: FLK-2; CD135; FLK2; STK1
Tractability: Small molecule: an approved drug acts on it; a structure with a bound ligand is known; a high-quality ligand is known; it has a binding pocket of medium quality; it belongs to a druggable protein family. Antibody: a drug acting on it is in phase 1 trials; its Gene Ontology location is reachable by antibodies, with high confidence; UniProt predicts a signal peptide or a membrane-spanning region. PROTAC: it is named in the literature on targeted protein degradation; UniProt records ubiquitination sites on it; ubiquitination databases record sites on it; a small molecule that binds it is known. Other modalities: a drug acting on it is in phase 2 or 3 trials.
Target class: TK protein kinase group; Kinase; Tyrosine protein kinase PDGFR family; Protein Kinase; Enzyme
Chemical probes: AC710, BPR1J-097, CCT 137690, FLT3-IN-1, HG-7-85-01 (high quality), JH-IX-179 (high quality), ORANTINIB, PD 082106, PD070152, PD080799, PD080801, PD080809, PD080815, PD080853, PD080977, PD081055, PD081115, PD081197, PD081424, PD081448, and 63 more
Safety:
Unwanted effects reported when the protein is acted on. In parentheses: how it was acted on, where the effect was seen, and who reports it.
myelosuppression (source: ClinPGx)
Gene: Protein-coding gene on chromosome 13 (28,003,274 to 28,100,592, reverse strand). Ensembl gene ENSG00000122025.
Subcellular location: Membrane; Endoplasmic reticulum lumen
Subcellular location (Human Protein Atlas): Endoplasmic reticulum
Pathways (Reactome):
Disease: Constitutive Signaling by Aberrant PI3K in Cancer; FLT3 mutants bind TKIs; FLT3 signaling by CBL mutants; KW2449-resistant FLT3 mutants; STAT5 activation downstream of FLT3 ITD mutants; Signaling by FLT3 ITD and TKD mutants; crenolanib-resistant FLT3 mutants; gilteritinib-resistant FLT3 mutants; lestaurtinib-resistant FLT3 mutants; linifanib-resistant FLT3 mutants; midostaurin-resistant FLT3 mutants; pexidartinib-resistant FLT3 mutants; ponatinib-resistant FLT3 mutants; quizartinib-resistant FLT3 mutants; semaxanib-resistant FLT3 mutants; sorafenib-resistant FLT3 mutants; sunitinib-resistant FLT3 mutants; tamatinib-resistant FLT3 mutants; tandutinib-resistant FLT3 mutants
Immune System: FLT3 Signaling; FLT3 signaling through SRC family kinases; Negative regulation of FLT3; STAT5 Activation
Signal Transduction: PI3K Cascade; PI5P, PP2A and IER3 Regulate PI3K/AKT Signaling; PIP3 activates AKT signaling; RAF/MAP kinase cascade
Gene Ontology:
Molecular function: protein binding; cytokine receptor activity; growth factor binding; phosphatidylinositol 3-kinase activator activity; protein tyrosine kinase activity; transmembrane receptor protein tyrosine kinase activity; vascular endothelial growth factor receptor activity; ATP binding; nuclear glucocorticoid receptor binding; protein kinase activity; protein-containing complex binding; transmembrane signaling receptor activity
Biological process: hemopoiesis; B cell differentiation; cell migration; cell surface receptor protein tyrosine kinase signaling pathway; cellular response to cytokine stimulus; common myeloid progenitor cell proliferation; cytokine-mediated signaling pathway; dendritic cell differentiation; leukocyte homeostasis; lymphocyte proliferation; myeloid progenitor cell differentiation; peptidyl-tyrosine phosphorylation; positive regulation of cell population proliferation; positive regulation of MAP kinase activity; positive regulation of MAPK cascade; positive regulation of phosphatidylinositol 3-kinase/protein kinase B signal transduction; positive regulation of tyrosine phosphorylation of STAT protein; pro-B cell differentiation; protein autophosphorylation; regulation of apoptotic process; cell surface receptor signaling pathway; cellular response to glucocorticoid stimulus; liver regeneration; vascular endothelial growth factor signaling pathway
Cellular component: endosome membrane; plasma membrane; receptor complex; endoplasmic reticulum lumen; membrane; protein-containing complex
Genetic constraint (gnomAD): Loss-of-function variants: 29 observed, 84.57 expected, observed/expected ratio (o/e) 0.34, 90% interval 0.25 to 0.47. The upper end of that interval is the gene's LOEUF score, 0.47, which puts it in group 2 of 6, group 1 being the genes least tolerant of losing a copy. Missense variants: 730 observed, 854.12 expected, observed/expected ratio (o/e) 0.85, 90% interval 0.8 to 0.91. Synonymous variants: 293 observed, 320.16 expected, observed/expected ratio (o/e) 0.92, 90% interval 0.83 to 1.01.
Gene-disease validity (ClinGen):
ClinGen rates the evidence that FLT3 causes each of these diseases.
leukemia, acute myeloid, susceptibility to (autosomal dominant): Limited. An inherited susceptibility or predisposition to developing leukemia, acute myeloid.
Cancer hallmarks: escaping programmed cell death (promotes); proliferative signalling (promotes); suppression of growth (promotes)
Homologues: Orthologues: chimpanzee FLT3 (99% identical), pig FLT3 (92% identical), rabbit FLT3 (91% identical), dog FLT3 (91% identical), guinea pig FLT3 (90% identical), mouse Flt3 (86% identical), rat Flt3 (85% identical), macaque FLT3 (79% identical), tropical clawed frog flt3 (48% identical). Paralogues in human: CSF1R (30% identical), PDGFRA (29% identical), KIT (29% identical), PDGFRB (26% identical), KDR (25% identical), FLT4 (25% identical), FLT1 (24% identical), FGFR2 (20% identical), FGFR1 (20% identical), FGFR3 (20% identical), FGFR4 (19% identical), TIE1 (19% identical), and 41 more.
Diseases named in the same sentence as FLT3 in open-access papers:
FLT3 is named in the same sentence as 286 diseases in open-access papers, as found by Europe PMC text mining. Sharing a sentence is not in itself a finding about the gene and the disease. The quoted sentences say what the papers report.
acute myeloid leukemia (1,032 papers, 2007 to 2026). Acute myeloid leukemia (AML) is a group of neoplasms arising from precursor cells committed to the myeloid cell-line differentiation. "Background/Objectives: The emergence of FLT3 inhibitors (FLT3i) has radically transformed the prognostic and therapeutic landscape for FLT3-mutated Acute Myeloid Leukemia, stimulating the need for comprehensive and structured clinical guidance." (PMID 41827706, 2026). "Gilteritinib is a selective FLT3 inhibitor approved for the treatment of relapsed or refractory (R/R) FLT3‐mutated acute myeloid leukemia (AML) following ≥ 1 prior line of therapy." (PMID 41273181, 2026). "Approximately 30% of patients with acute myeloid leukemia (AML) harbor FMS-like tyrosine kinase 3 (FLT3) mutations, which are associated with poor overall survival." (PMID 41487332, 2026). "Using the drug-resistant FLT3 D835Y mutation in acute myeloid leukemia as a model, we prepared wild-type FLT3 (FLT3-WT) and FLT3-D835Y plasmids." (PMID 41505099, 2026). "Overexpression of the wild type (WT) or oncogenic forms of FLT3 is closely associated with the development of acute myeloid leukaemia (AML)." (PMID 40941028, 2025). "Background/Objectives: Acute myeloid leukemia (AML) with FLT3 internal tandem duplication (FLT3-ITD) mutations carries a poor prognosis." (PMID 40725802, 2025). "FMS‐like tyrosine kinase‐3 (FLT3) is a class III receptor tyrosine kinase (RTK) that is the most frequently mutated gene in acute myeloid leukemia (AML)." (PMID 39395205, 2025). "FF-10101 was originally developed as an FLT3 inhibitor and strongly suppresses the proliferation of acute myeloid leukemia (AML) with FLT3 mutations." (PMID 39782686, 2025). "The discovery of activating mutations in the FLT3 receptor in approximately 30% of acute myeloid leukemia (AML) patients identified FLT3 as a therapeutic target." (PMID 41226551, 2025). "Oncogenic mutations in the FLT3 gene, resulting in constitutively active FLT3 variants, are frequently found in patients with acute myeloid leukaemia (AML)." (PMID 40941028, 2025). "FLT3 mutations are among the most frequent genetic alterations in adult acute myeloid leukemia (AML) and are associated with heterogeneous clinical outcomes." (PMID 40565186, 2025). "Flt3 mutations increase the sensitivity of acute myeloid leukemia cells to ferroptosis by triggering lipid oxidative stress." (PMID 40796725, 2025). "FMS-like tyrosine kinase 3 (FLT3) mutation is reported in 30% of acute myeloid leukemia (AML) cases, with the internal tandem duplication (ITD) representing the most common type of FLT3 mutation (FLT3-ITD; approximately 25% of all AML cases)." (PMID 40725802, 2025). "Activating somatic mutations in the gene encoding FMS-like tyrosine kinase 3 (FLT3) are present in approximately one-third of patients with acute myeloid leukemia (AML)." (PMID 41026969, 2025). "Sorafenib has been approved for liver cancer and kidney cancer, and has also shown therapeutic efficacy in acute myeloid leukemia (AML) patients with FLT3-ITD mutations, leading to improved patient survival." (PMID 40725394, 2025). "Mutations in the nucleophosmin-1 (NPM1) gene and the internal tandem duplications (ITDs) of the fms-related tyrosine kinase 3 (FLT3) gene constitute two of the commonest mutations in Acute Myeloid Leukemia (AML), with a significant impact on prognosis." (PMID 40002262, 2025). "Though FLT3 inhibitors have been primarily developed and approved for the treatment of FLT3-mutated acute myeloid leukemia (AML), their role in solid tumors, particularly CRC, remains underexplored." (PMID 40427072, 2025). "FLT3 mutations are found in about 30% of patients with acute myeloid leukemia (AML), making it one of the most frequently mutated genes in this aggressive hematologic malignancy." (PMID 40547482, 2025).
acute myeloid leukemia (continued). "This interim analysis of a phase 1/2, open-label, single-arm study assessed the safety, efficacy, and pharmacokinetics of gilteritinib plus chemotherapy in adults with newly diagnosed FLT3 mutation-positive acute myeloid leukemia." (PMID 39503987, 2025). "Approximately 20% to 30% of patients with acute myeloid leukemia carry activating mutations in fms related receptor tyrosine kinase 3 (FLT3), particularly the FLT3-ITD mutation, which is a critical target for therapy." (PMID 40746885, 2025). "FLT3-ITD mutations are among the most common genetic alterations in acute myeloid leukemia (AML) and are associated with poor clinical outcomes." (PMID 40951362, 2025). "Gilteritinib, a FDA-approved small-molecule inhibitor, is used for the treatment of patients with FLT3-mutated acute myeloid leukemia." (PMID 40157901, 2025). "The FMS-like tyrosine kinase 3 (FLT3) gene mutation is among the most prevalent genetic alterations in Acute myeloid leukemia (AML), occurring in approximately 30% of cases." (PMID 41479777, 2025). "FLT3-mutated acute myeloid leukemia (AML) with central nervous system (CNS) involvement poses therapeutic challenges." (PMID 40083897, 2025). "This epigenetic mechanism, combined with FLT3 signaling inhibition, underscores its potential in treating FLT3-mutated acute myeloid leukemia." (PMID 40520993, 2025). "Alkynyl nicotinamide compounds HSN608 and HSN748 are more effective than FDA-approved FLT3 inhibitors against FLT3ITD in relapsed/refractory acute myeloid leukemia models bearing combination mutations." (PMID 38950330, 2024). "Since FLT3 mutations were found in about one-third of patients with acute myeloid leukemia, several targeted FLT3 inhibitors have been developed." (PMID 38254833, 2024). "Gilteritinib, another FLT3 inhibitor approved for the treatment of refractory acute myeloid leukemia, has been associated with retinal hemorrhages, which occurred in 7.72% of patients." (PMID 39728071, 2024). "The internal tandem duplication (ITD) mutation of the FMS-like receptor tyrosine kinase 3 (FLT3-ITD) is the most common mutation observed in approximately 30% of acute myeloid leukemia (AML) patients." (PMID 38696033, 2024). "Mutations of this kinase are frequently associated with acute myelogenous leukemia, and FLT3 inhibitors can be used to treat this disease." (PMID 38374336, 2024). "The presence of mutations in the internal tandem duplication (ITD) of the Fms-like tyrosine kinase 3 gene (FLT3/ITD) in acute myeloid leukemia (AML) is considered an unfavorable genetic alteration associated with a poor prognosis." (PMID 38994204, 2024). "Internal tandem duplications in the FMS-like tyrosine kinase-3 (FLT3-ITD) are common mutations in acute myeloid leukemia (AML)." (PMID 39300221, 2024). "The tyrosine kinase domain of the FMS-Like tyrosine kinase 3 (FLT3-TKD) is recurrently mutated in acute myeloid leukemia (AML)." (PMID 38891959, 2024). "Abnormal activation of FLT3 in acute myeloid leukemia is closely associated with disease occurrence and development." (PMID 38671491, 2024). "The high prevalence of FLT3 -activating mutations in haematological malignancies, especially in acute myeloid leukaemia (AML), highlights the importance of this gene in leukemogenesis." (PMID 38049555, 2024). "The fms-like tyrosine kinase receptor 3 (FLT3) gene is overexpressed in up to 93% and mutated in over 30% of primary acute myeloid leukemia (AML)." (PMID 38666914, 2024). "Activating mutations of the fms-like tyrosine kinase 3 (FLT3) gene are associated with a poor outcome in patients with acute myeloid leukemia." (PMID 38530400, 2024). "Consistent with this, it has been shown that inhibition of TGF-β and CXCR4 results in improved survival in an fms-related receptor tyrosine kinase 3 (flt3)-mutated acute myeloid leukemia (AML) model." (PMID 38396852, 2024).
acute myeloid leukemia (continued). "This study aimed to assess the efficacy and safety of gilteritinib combined with chemotherapy in treating newly diagnosed FLT3-mutated acute myeloid leukemia(AML)." (PMID 39765355, 2024). "Acute myeloid leukemia carrying FMS-like tyrosine kinase receptor-3 (FLT3) mutations is a fatal blood cancer with a poor prognosis." (PMID 38257023, 2024). "Lastly, lestaurtinib and midostaurin were developed for the treatment of acute myeloid leukemia with a positive FLT3 mutation." (PMID 38474445, 2024). "In the present case, the final diagnosis was acute myeloid leukemia (FLT3, DNMT3A, U2AF1, and SMC3 mutations; KMT2A amplification; high-risk) with adenocarcinoma of the cardia." (PMID 39121277, 2024). "FMS-like tyrosine kinase 3 (FLT3) mutations are genetic changes found in approximately thirty percent of patients with acute myeloid leukemia (AML)." (PMID 39273395, 2024). "This preliminary study provides first-time prevalence estimates for FLT3-ITD mutation in acute myeloid leukemia patients from the West region of Algeria." (PMID 38915455, 2024). "FLT3 mutations are common in acute myeloid leukemia (AML) and are often associated with poorer outcomes and higher relapse rates." (PMID 39199635, 2024). "FLT3 inhibitors such as gilteritinib and midostaurin target acute myeloid leukemia with FLT3 mutations, while FGFR inhibitors such as erdafitinib are used for urothelial carcinoma." (PMID 39337925, 2024). "The patient was diagnosed with acute myeloid leukemia (FLT3, DNMT3A, U2AF1, and SMC3 mutations; KMT2A amplification; high-risk) and adenocarcinoma of the cardia." (PMID 39121277, 2024). "Mutations in FLT3, such as internal tandem duplications (ITDs) and point mutations in thetyrosine kinase domain, are frequently found in acute myeloid leukemia (AML)." (PMID 39132250, 2024). "FLT3-ITD is a common driver mutation that manifests as a high leukemia burden in patients with acute myeloid leukemia with a poor prognosis." (PMID 38322112, 2024). "FMS-like tyrosine kinase 3 (FLT3) internal tandem duplication (ITD) mutations in acute myeloid leukemia (AML) are associated with poor prognosis and therapy resistance." (PMID 39408703, 2024). "FMS‐like tyrosine kinase 3 (FLT3) is one of the most commonly mutated genes in acute myeloid leukemia (AML)." (PMID 39691247, 2024). "Midostaurin is a multi-kinase inhibitor approved for the treatment of systemic mastocytosis and acute myeloid leukemia with FLT-3 activating mutations." (PMID 38724853, 2024). "Approximately 30% of newly diagnosed acute myeloid leukemia (AML) patients exhibit activating mutations in FMS-related tyrosine kinase-3 (FLT3), with this incidence decreasing with age." (PMID 39199635, 2024). "Activity-enhancing mutations of Flt3 are key drivers of acute myeloid leukemia (AML) and can be found in 15–35% of AML patients." (PMID 37945814, 2024). "Acute myeloid leukemia (AML) patients with a Fms‐like tyrosine kinase 3 (FLT3) mutation have a high incidence of relapse despite allogeneic hematopoietic stem cell transplantation (allo‐HSCT) and a subsequent poor prognosis." (PMID 36411731, 2023). "Specifically, FLT3 internal tandem duplications (FLT3ITD) are found in 30–40% of all patients with acute myeloid leukemia (AML) and are associated with poor clinical prognosis due to relapse after chemotherapy." (PMID 36739348, 2023). "The fms-like tyrosine kinase 3 (FLT3) inhibitor gilteritinib improved the survival of patients with relapsed or refractory (R/R) FLT3-mutated acute myelogenous leukemia (AML) in the phase 3 ADMIRAL trial." (PMID 36526260, 2023). "Fms-like tyrosine kinase type III (FLT3) inhibitors have been shown to induce significant clinical responses in patients with acute myeloid leukemia (AML) harboring FLT3 mutations." (PMID 37174019, 2023).